ENSG00000213204 (novel transcript, C6orf165-SLC35A1 readthrough)
Gene: Protein-coding gene on chromosome 6 (87,408,012 to 87,511,634, forward strand). Ensembl gene ENSG00000213204.
Genetic constraint (gnomAD): Missense variants: 513 observed, 612.24 expected, observed/expected ratio (o/e) 0.84, 90% interval 0.78 to 0.9. Synonymous variants: 199 observed, 212.24 expected, observed/expected ratio (o/e) 0.94, 90% interval 0.83 to 1.05.